BDNF (brain derived neurotrophic factor)
Diseases named in the same sentence as BDNF in open-access papers (continued):
Sharing a sentence is not in itself a finding about the gene and the disease.
schizophrenia (continued). "To date, preclinical and clinical studies have reported a generalized decrease in serum and brain BDNF levels in multiple neurodegenerative and psychiatric disorders, including PD, AD, HD, MDD, and schizophrenia." (PMID 35887357, 2022). "Thus, decreased serum BDNF levels may indicate neuropathological alterations in the brain, confirming the neurodevelopment hypothesis, which claims that schizophrenia is the outcome of pathological processes that begin during prenatal and postnatal central nervous system development." (PMID 35757201, 2022). "Relationships between different BDNF and CREB genotypes and PANSS scores in the schizophrenia group p < 0.05." (PMID 35368680, 2022). "When looking at low levels of peripheral BDNF in FEP, it has been demonstrated that different areas of the brain in patient with schizophrenia have decreased concentrations of BDNF." (PMID 35447946, 2022). "Brain-derived neurotrophic factor (BDNF), a neurotrophin, and matrix metalloproteinase 9 (MMP-9), a gelatinase B, are the promising candidate genes for schizophrenia." (PMID 36325525, 2022). "In summary, we conducted a clinical study to clarify the relationship between serum BDNF levels and depressive symptoms in patients with FEDN schizophrenia." (PMID 35757201, 2022). "In vivo, we studied the gene expression of DCX, Sox2, BDNF, and NeuN in the SVZ and HIP in an MK-801-induced animal schizophrenia model." (PMID 35887056, 2022). "The allele and genotype frequencies of three SNPs (rs11030101, rs2030324, and rs6265) in the BDNF gene and two SNPs in the CREB gene (rs6740584 and rs2551640) were compared between the schizophrenia and control groups." (PMID 35368680, 2022). "In humans, lower serum BDNF levels have been seen in patients with major depressive disorder (MDD), bipolar disorder (BD), schizophrenia, eating disorder, obsessive-compulsive disorder (OCD) and alcohol dependency." (PMID 35114967, 2022). "Similar doses of crocin (i.p., 25 or 50 mg/Kg b.w.)also exerted neuroprotective effects in a rat model of MK-801-elicited schizophrenia by modulating the expression of silent information regulator-1 (SIRT1) and brain-derived neurotrophic factor (BDNF)." (PMID 36558528, 2022). "Brain-derived neurotrophic factor (BDNF) is a neurotrophin that regulates neuronal survival and growth, which, in post-mortem studies, has been found to be reduced in the PFC of schizophrenia patients." (PMID 35963926, 2022). "Correlations between BDNF and socio-demographic characteristics and PANSS scores in schizophrenia patientsa." (PMID 35757201, 2022). "In this mini-review, we will discuss a potential pathogenetic mechanism for schizophrenia involving DTNBP1, BDNF, and inhibitory transmission." (PMID 35815020, 2022). "We analyzed the distribution of BDNF (rs11030101, rs2030324, and rs6265) and CREB gene (rs6740584 and rs2551640) haplotypes in the schizophrenia and control groups." (PMID 35368680, 2022). "Another study found that patients with schizophrenia and T2DM (type 2 diabetes) showed elevated BDNF levels and improved cognitive function." (PMID 35194435, 2021). "The perturbation of BDNF/TrkB signaling in NHE6 KO mice is consistent with low levels of BDNF and TrkB receptor in schizophrenia patients." (PMID 34445065, 2021). "BDNF, GDNF, NGF and Klotho levels were lower in schizophrenia patients than in healthy controls; and, in schizophrenia, on the 20th day of treatment, there was a statistically significant increase in BDNF compared to the 1st day." (PMID 34763683, 2021). "Our finding of lower BDNF serum levels in LLS patients compared with the aged-matched cohort, extended previous findings in younger and middle-aged schizophrenia." (PMID 34239458, 2021). "In this study, the relationship between cognitive functions and BDNF, GDNF, NGF and Klotho levels in 41 patients diagnosed with schizophrenia who had acute psychotic exacerbation and in 43 healthy controls was examined." (PMID 34763683, 2021).
schizophrenia (continued). "Furthermore, prevailing evidence supports higher methylation levels and decreased expression of BDNF in patients with schizophrenia, a fact that may explain the impaired GABAergic signaling and the reduced hippocampal volume observed in this cohort compared to controls." (PMID 34073101, 2021). "For example, Tang and colleagues revealed a low BDNF and GDNF serum level in Chinese male patients with schizophrenia." (PMID 35095724, 2021). "Brain-derived neurotrophic factor (BDNF), glial cell line-derived neurotrophic factor (GDNF) and neuronal growth factor (NGF) are among the most studied neurotrophic factors in schizophrenia." (PMID 34763683, 2021). "Our study aims to explore the sex differences in the relationship between serum BDNF levels and HOMA-IR in patients with chronic schizophrenia (CS)." (PMID 34234699, 2021). "In the hippocampus of MK-801-induced schizophrenia rat model, RSV enhanced silent information regulator 1 (SIRT1) and brain derived neurotrophic factor (BDNF) expression and alleviated oxidative stress." (PMID 32793005, 2020). "After a 24-month olanzapine treatment (unspecified dose), 95 schizophrenic patients with metabolic syndrome showed lower concentrations of BDNF (P < 0.012) and higher values of TNF-α as compared to 121 patients only diagnosed with schizophrenia." (PMID 32373066, 2020). "However, if future studies confirm that dysbiosis predicts schizophrenia, then it could link a number of observations in schizophrenia patients, such as raised inflammatory markers or altered BDNF and kynurenate levels, and thus contribute to the increasingly complex picture of its etiology." (PMID 32226399, 2020). "In conclusion, RSV showed neuroprotective effect on MK-801-induced schizophrenia rat model through regulating SIRT1 and downstream BDNF expression in the hippocampus." (PMID 32793005, 2020). "In our study, we detected by LC-MS/MS that these proteins, specifically BDNF, GMF-β, and the 115-kDa isoform of RAB3GAP1, are downregulated in schizophrenia, with significantly reduced levels being detected in the plasma of schizophrenic patients." (PMID 31849731, 2019). "Brain-derived neurotrophic factor (BDNF) has been established as a candidate molecule for the pathophysiology of neuropsychiatric disorders, such as schizophrenia and major depressive disorder (MDD)." (PMID 31027379, 2019). "We corroborated by LC-MS/MS and Western blot that plasmatic BDNF is decreased in both FES and chronic schizophrenia." (PMID 31849731, 2019). "In the present study, we investigated the effect of MK-801 on neuron-derived BDNF expression in rats and in primary hippocampal neurons treated with MK801 as schizophrenia models." (PMID 31396062, 2019). "According to various studies showing the ability of PPARγ agonists to induce the expression of BDNF, it is possible to propose a possible effect of drugs, such as RSG, in improving cognitive symptoms typical of schizophrenia." (PMID 31614739, 2019). "Although there have been inconsistencies in the studies that investigated the BDNF and GDNF levels in patients with schizophrenia; the majority of the studies revealed that these two NFs are closely related to the pathological process of this disease." (PMID 31420036, 2019). "Thus, alterations in BDNF may play a role in the pathophysiology of schizophrenia." (PMID 32116676, 2019). "PRS adult offspring showed alterations in the epigenetic regulation of schizophrenia-related gene as reelin, GAD67, BDNF, and mGlu2/3 receptors." (PMID 30564095, 2018). "The majority of studies addressing G × E interactions in schizophrenia spectrum phenotypes and BD have focused on the effect of variation in the COMT, BDNF, and FKBP5 genes, showing interactions with cannabis use and childhood trauma." (PMID 28822116, 2018).
schizophrenia (continued). "Parallel and multistep analysis in this research showed that SLC1A1, DRD2, DRD4, BDNF, ESR1, CDH2, GRIN2B, TNFa, GABBR1, and OLIG2 are common genes between schizophrenia and OCD which ESR1, DRD2, GABBR1, TNFa, and CDH2 are the most important individuals." (PMID 31086558, 2018). "Evidence for the involvement of the α2C-AR in the expression of BDNF has been demonstrated in the SIR animal model of schizophrenia, where SIR rats present with reduced striatal BDNF levels." (PMID 28855875, 2017). "However, the PGC did not rank any SNPs in GLS1 or BDNF into the top 108 schizophrenia risk loci." (PMID 28659829, 2017). "Brain-derived neurotrophic factor (BDNF) was involved in energy metabolism and the pathophysiology of schizophrenia, but differently in males and females." (PMID 28562580, 2017). "In Conclusion, our findings suggest the role of TOX, ADIPOQ and BDNF in weight and WHR gain induced by atypical antipsychotics in schizophrenia subjects." (PMID 28327672, 2017). "The change in BDNF expression leads to the cognitive dysfunction of schizophrenia patients, and antagonists of the NMDA receptor can produce schizophrenia symptoms." (PMID 28881854, 2017). "For example, a reduction in BDNF concentrations has been reported in the prefrontal cortex (PFC) and hippocampus in schizophrenia compared with controls." (PMID 27783051, 2016). "Later, D-amino acid oxidase activator gene and brain derived neurotrophic factor gene became also of great interest, but it seems that no actual evidence was found in this matter, mainly due to the fact that most of these genes are reported as schizophrenia susceptibility genes too." (PMID 27563374, 2016). "We investigated the serum levels of brain-derived neurotrophic factor (BDNF), proBDNF and plasma 3-methoxy-4-hydroxyphenylglycol (MHPG) levels in patients with chronic schizophrenia." (PMID 26770258, 2016). "Given that exercise and yoga therapy have a positive effect in schizophrenia, further trials with exercise training including yoga under conditions with moderate intensity and duration for schizophrenia patients could be designed to determine their effect on BDNF levels." (PMID 27783051, 2016). "We also reconfirmed that serum BDNF and plasma MHPG levels were significantly reduced in the 68 chronic schizophrenia patients compared to healthy controls." (PMID 26770258, 2016). "We suggest that although most people withschizophrenia may synthesize less cortical BDNF, even when BDNF levels are normal orincreased, there still may be a block in the function of BDNF through increased presence oftruncated trkB receptors within the brains of people with schizophrenia." (PMID 25162472, 2015). "BDNF mRNA levels were also significantly decreased in layer V and/or VI of STG in schizophrenia, BPD and MDD." (PMID 24802307, 2014). "Bonferroni testing showed that BDNF mRNA levels were significantly reduced in BPD (P=0.008; 26% reduction), schizophrenia (P=0.008; 27% reduction) and MDD (P=0.0005; 34% reduction) compared with controls." (PMID 24802307, 2014). "In the present study we investigated the possible association of polymorphisms from five candidate genes RGS4, SLC6A3, PIP4K2A, BDNF, PI4KA with response to antipsychotic in variably ill schizophrenia patients." (PMID 25025909, 2014). "BDNF mRNA levels were significantly decreased in layers IV and V of DLPFC in schizophrenia patients, in layer VI of ACC in schizophrenia and MDD and in layer VI of ITG in schizophrenia, BPD and MDD." (PMID 24802307, 2014). "It is possible that, as in the case of schizophrenia, childhood maltreatment interacts with an underlying developmental vulnerability to lead to symptom formation in GID/GD; alternately, trauma-related release of stress hormones may lower BDNF levels, affecting childhood brain development." (PMID 25548672, 2014).
schizophrenia (continued). "Our data illustrate the interaction between two signaling pathways (BDNF and NRG1), which are well studied for their roles in synaptic plasticity and in the pathophysiology of many neuropsychiatric disorders including schizophrenia." (PMID 25052836, 2014). "In present study, MDR results suggested interaction between RGS4_rs2842026-SLC6A3_rs2975226 in schizophrenia patients of LSG and between BDNF_rs7103411-BDNF_rs1491851-SLC6A3_rs40184 in severely ill patients for their inadequate treatment response." (PMID 25025909, 2014). "Thus, it is possible that deficient levels of BDNF might have led to aberrations involving critical brain regions (like inferior parietal lobule, parahippocampal, and posterior cingulate gyri) resulting in genesis of FRS in schizophrenia." (PMID 23847552, 2013). "It regulates BDNF, altering the expression of downstream GABAergic transcripts (NPY, SST and PV) in schizophrenia patients." (PMID 20156358, 2010). "The key findings from the present study are: First, gene expression of Spry2 and BDNF, a known inducer of Spry2, are down-regulated in the DLPFC of schizophrenia and bipolar subjects." (PMID 18335055, 2008). "Our earlier research revealed for the first time a novel connection between specific gene polymorphisms related to neuroplasticity and protein kinases (including MAPK, BDNF, GSK3β, and AKT1) and the development of schizophrenia symptoms that predict a poor disease outcome." (PMID 41283305, 2025). "We found significant decreases in BDNF, TrkBTK+ and NURR1 (14–18%) and increases in TrkBTK- and p75 (18–35%) mRNA levels in schizophrenia compared to controls (all p < 0.05), with exacerbation of changes identified in high inflammation schizophrenia." (PMID 40335479, 2025). "So far, reductions, increases, and the lack of changes in BDNF levels have been reported, and there is no consensus on the usefulness of BDNF as a schizophrenia biomarker or a predictor of response to therapy." (PMID 41010622, 2025). "Altogether, the changes in BDNF, NURR1 and TrkB that are exacerbated in high inflammation schizophrenia cases may allude to greater disease severity in this subset of patients." (PMID 40335479, 2025). "This CREB-dependent mechanism may synergize with GSK3β-mediated pathways, as HERV-W env also enhances CREB phosphorylation to upregulate BDNF and dopamine receptor D3 (DRD3), contributing to excitatory-inhibitory imbalances in schizophrenia." (PMID 41200560, 2025). "Here, we report that higher cytokines and lower BDNF co-occur in the midbrain of people with schizophrenia, supporting that this interaction is not just found in serum or plasma but extends to brain tissue." (PMID 40335479, 2025). "More specifically, there was a greater mean decrease in BDNF IV (30.8%; p = 0.007), NURR1 (30.1%; p = 0.001) and TrkBTK+ (23.5%; p < 0.001) mRNA levels when comparing high inflammation schizophrenia cases to low inflammation controls than when just examining diagnostic changes alone." (PMID 40335479, 2025). "High levels of BDNF mRNA were also observed in some microglia/macrophages in high inflammation schizophrenia cases, but not in low inflammation schizophrenia or controls." (PMID 40335479, 2025). "Our data replicated this finding, although a report showed differences in BDNF levels between patients with schizophrenia and healthy controls, rather than GDNF levels." (PMID 39886050, 2024). "We probed the potential association and eventual stability of neuropsychological profiles and serum BDNF concentrations with lifetime suicide ideation and attempts (LSI and LSA, respectively) in individuals with schizophrenia (SCZ) and schizoaffective disorder (SCA) in a 2-year follow-up study." (PMID 39063164, 2024). "In relation to the healthy control, the schizophrenia group exhibited elevated mir-195-5p in peripheral blood, with a negative correlation regarding BDNF." (PMID 39452910, 2024).
schizophrenia (continued). "They observed an interaction between low BDNF and high IL-8 concentrations, which were positively correlated with executive dysfunction as measured by verbal fluency tests (VFT) and Wisconsin card sorting tests (WCST) in patients with schizophrenia." (PMID 38793070, 2024). "Serum levels of GDNF and BDNF were significantly lower in patients with schizophrenia compared to healthy controls at baseline (GDNF: 304.838 ± 18.236 pg/ml vs. 378.534 ± 24.397 pg/ml, p = 0.012; BDNF: 275.821 ± 21.447 pg/ml vs. 370.983 ± 33.849 pg/ml, p = 0.010)." (PMID 39886050, 2024). "A potential mechanism is the upregulation of brain-derived neurotrophic factor (BDNF) during exercise, which preliminary evidence suggests may mediate cognitive improvements in schizophrenia." (PMID 39309156, 2024). "Analysis of BDNF gene haplotypes revealed that the rs11030101/rs2030324/rs6265 AAC haplotype was more common in patients with schizophrenia than in healthy individuals, and that negative symptoms were more pronounced in rs11030101-A homozygous patients." (PMID 38646100, 2024). "Autism spectrum disorder (ASD), Rett syndrome (RTT), and schizophrenia (SCZ) are three neurodevelopmental disorders that show this imbalance derived from impairments within the GABAergic brain network and have been related with BDNF-signaling disruptions." (PMID 39125882, 2024). "Surprisingly, our findings indicate that schizophrenia patients who use cannabis have elevated BDNF levels as opposed to schizophrenia patients who do not use cannabis." (PMID 38376038, 2024). "In the complete group of patients with schizophrenia, the BDNF plasma levels were not significantly correlated with the MoCA scores (p = 0.90), according to the Spearman Rho test." (PMID 37445746, 2023). "The study also found a negative effect of MDA and a positive effect of BDNF on the severity of deficit symptoms in schizophrenia." (PMID 36979300, 2023). "It was pointed out that decreased BDNF levels are not specific to mood disorders, and a similar decrease was also observed in schizophrenia or dementia." (PMID 36831706, 2023). "Therefore, it is clear that new studies to evaluate BDNF levels after ECT that will take into account antipsychotic treatment, the heterogeneity of schizophrenia itself and patients’ characteristics are required." (PMID 37685795, 2023). "We may suspect that the BNDF levels of difficult-to-treat schizophrenia patients are more resistant to increase with treatment and may take some time after the last ECT course when an increase in the BDNF serum level will be gained." (PMID 37685795, 2023). "Increased susceptibility to apoptotic mechanisms in schizophrenia with relevance to synaptic or dendritic loss could be the consequence of both glutamate excitotoxicity and oxidative stress playing a prominent role, as well as the lack of neuroprotective factors (e.g., BDNF)." (PMID 37107350, 2023). "Studies have shown significantly reduced brain-derived neurotrophic factor (BDNF), nerve growth factor (NGF), and NGF receptor (NGFR ) levels in the prefrontal cortex (PFC) and the cerebrospinal fluid (CSF) of subjects diagnosed with schizophrenia." (PMID 36979236, 2023). "Alternatively, nonpharmacological interventions such as environmental enrichment or exercise may be beneficial in both schizophrenia and METH psychosis by enhancing BDNF expression in the brain." (PMID 37626786, 2023). "Additionally, our previous research suggested that CRP, IL10, and BDNF, which are regulated by ERVW-1, can be used as serum biomarkers of schizophrenia." (PMID 37376599, 2023). "For the time being, there are still no conclusive results regarding the BDNF levels in the serum of schizophrenia patients with depressive symptoms." (PMID 35757201, 2022).